TPRXL (tetrapeptide repeat homeobox like (pseudogene))
Description:
Transcription factor required for zygotic genome activation (ZGA), a critical event in early embryonic development during which the developmental control passes from maternally provided mRNAs to the expression of the zygotic genome after fertilization. Protein produced from maternal transcripts that binds and activates expression of key ZGA marker genes, such as NANOGNB, ZSCAN4, DUXB, KLF5 and DPPA3. Binds to regulatory DNA sequences containing a 5'-TAATCC-3' sequence motif (By similarity).
Synonyms: FLJ35107; TPRX3P
Gene: Transcribed processed pseudogene on chromosome 3 (14,064,203 to 14,065,442, forward strand). Ensembl gene ENSG00000180438.
Subcellular location: Nucleus
Diseases named in the same sentence as TPRXL in open-access papers:
TPRXL is named in the same sentence as 4 diseases in open-access papers, as found by Europe PMC text mining. Sharing a sentence is not in itself a finding about the gene and the disease. The quoted sentences say what the papers report.
gastric cancer (1 paper, 2015). A primary or metastatic malignant neoplasm involving the stomach. "However, most of the lncRNAs such as DRD5, FMO6P, SNAR-A3 and TPRXL showed in our microarray haven’t been identified and need further investigation to clarify their roles in gastric cancer." (PMID 25928635, 2015).
TPRXL also shares sentences with these, for which no sentence is quoted: adenocarcinoma (1 paper); lung carcinoma (1); squamous cell carcinoma (1).